INS (insulin)
Diseases named in the same sentence as INS in open-access papers (continued):
Sharing a sentence is not in itself a finding about the gene and the disease.
Insulin resistance (continued). "Further studies were planned to explore the mechanism by which EA stimulation at the Zusanli acupoint improves insulin resistance from the viewpoint of molecular biology and to examine the neuroendocrine effect and its relationship to insulin signal proteins." (PMID 25024728, 2014). "T2DM is a multifactorial metabolic disease mainly characterized by hyperglycemia, but before the occurrence of overt hyperglycemia, peripheral insulin resistance (IR) leads to compensatory insulin hypersecretion by pancreatic islets." (PMID 25313308, 2014). "The failure of this translocation in response to insulin is one of the steps in the development of insulin resistance and type 2 diabetes." (PMID 24971309, 2014). "Thus, we hypothesized that this gender difference in relationship between hs-CRP and MS and its components is already present during adolescence; and examined the association among markers of inflammation, insulin resistance and insulin clearance and adiposity in a group of obese adolescents." (PMID 24555754, 2014). "Defective GLUT4 translocation in muscle is a key feature of insulin resistance, but to date, defects are assigned to alterations in insulin-derived signals and the possible contribution of proper intracellular sorting of GLUT4 has not been analyzed." (PMID 24705014, 2014). "Type 2 diabetes develops when pancreatic β cells fail to secrete enough insulin in the face of insulin resistance or increased insulin demand, most likely due to β-cell exhaustion." (PMID 25120636, 2014). "Despite extensive research we have a rudimentary understanding of the molecular mechanisms that underpin insulin resistance in insulin target tissues." (PMID 24752197, 2014). "To examine the relationship between nSMase and insulin resistance, we first demonstrated that the levels of all three nSMases were increased under palmitate with attendant decrease in insulin stimulated Akt/PKB phosphorylation." (PMID 24892004, 2014). "Metformin is commonly considered as an insulin sensitizer as it enhances signaling through the insulin receptor, resulting in an decrease in insulin resistance and subsequent reduction in circulating insulin levels." (PMID 25289085, 2014). "Although a few synthetic antidiabetic drugs are available to combat the impaired insulin secretion, insulin resistance, and hyperglycemia that characterize type 2 diabetes mellitus, some of these drugs can have negative side effects at high doses." (PMID 24616741, 2014). "A HFD increased blood glucose, glycosylated hemoglobin, and fasting plasma insulin (33%, 15% and 70% increase, respectively), in conjunction with reduced oral glucose tolerance, indicating the manifestation of insulin resistance." (PMID 25028601, 2014). "Since skeletal muscle is the predominant site of insulin-mediated glucose disposal in the postprandial state, development of muscular insulin resistance will crucially impact on glucose homeostasis." (PMID 24203314, 2014). "We have previously shown that insulin plays an important role in the nutrient-induced insulin resistance." (PMID 24741073, 2014). "During insulin resistance, insulin mediated glucose oxidation comes down and hence fat becomes primary fuel source albeit overall oxidation is reduced." (PMID 24936385, 2014). "Further, it has been shown that low grade inflammation induces insulin resistance through altered insulin signaling in hepatocytes and peripheral tissues." (PMID 24555754, 2014). "The current exercise protocol has been effective in lowering plasma glucose (p = 0.05), insulin levels (p = 0.000) and insulin resistance (p = 0.02)." (PMID 25560330, 2014). "In states of insulin resistance, high insulin levels are detected; however, it is likely that only a small amount of that insulin is free to interact with the respective targets." (PMID 24995000, 2014).
Insulin resistance (continued). "High doses of insulin can induce insulin resistance in diabetic rats, whilst intermediate doses can maximally improve insulin sensitivity; therefore, studies investigating the optimal insulin dosage are required." (PMID 25187822, 2014). "Observing the molecular structure of NAC (N-acetyl-cysteine) highlighted the presence of a disulfide bridge that should facilitate the processing of proinsulin into insulin, a critical step to reduce insulin resistance." (PMID 24876842, 2014). "In contrast, hypothermia leads to insulin resistance and decreased insulin secretion and therefore, increases the blood sugar level." (PMID 25237582, 2014). "TEG decreases in the presence of insulin resistance and/or reduces insulin response to glucose load." (PMID 24711817, 2014). "The significant associations evidenced among the REGARDS population align with the general literature suggesting neighborhood associations with insulin and glucose outcomes among MESA participants and insulin resistance." (PMID 25539758, 2014). "It is widely accepted that impaired endothelium-dependent vasodilatation in the states of insulin resistance results in a decrease in insulin delivery to insulin-sensitive muscle tissue, and decreases glucose uptake in muscles." (PMID 23934358, 2014). "Secondly, chronic exposure to excess amount of slow- and long-acting insulin, glargine, induces moderate and tissue-specific insulin resistance." (PMID 24741073, 2014). "Insulin resistance in obesity leads to hypersecretion of insulin from β-pancreatic cells and two other hormones co-secreted with insulin, amylin, and preptin, also circulate at high levels in obesity." (PMID 24847313, 2014). "Increase in fasting insulin is one of the most important indications of insulin resistance in the present study." (PMID 25548795, 2014). "Insulin resistance and hyperinsulinemia are important risk factors for cardiovascular disease due, in part, to the VSM proliferative and pro-atherogenic actions of insulin." (PMID 24888351, 2014). "Type-2 diabetes (T2D), characterized by insulin resistance of target tissues and insufficient insulin secretion from pancreatic beta cells, is a prevalence disease that happened all around the world in high frequency." (PMID 25530976, 2014). "Obviously, mulberry BBE not only can reduce the abnormally elevated levels of serum insulin and ameliorate insulin resistance induced by STZ, but also it regulates dyslipidemia in diabetic mice." (PMID 25177729, 2014). "Insulin clearance was claimed as a target in the treatment of T2D given the role of hyperinsulinemia in the pathogenesis of insulin resistance." (PMID 24740421, 2014). "Serum insulin levels were higher in HF than NC, indicating that this mouse model is able to compensate for insulin resistance after prolonged HF treatment." (PMID 24505268, 2014). "Nevertheless, there is evidence that vitamin D inhibits fat accumulation, increases insulin synthesis and preserves pancreatic islet cells, decreases insulin resistance and reduces hunger, favoring obesity and T2DM control." (PMID 24747593, 2014). "Overcoming insulin resistance during surgery through exogenous administration of insulin can therefore be neuroprotective." (PMID 24941010, 2014). "Obesity, dyslipidemia, higher fasting plasma insulin, higher insulin resistance, and worsened β-cell function were found in subjects with T2D in childhood and adolescence." (PMID 25309595, 2014). "This reduction can contribute to insulin resistance through the inhibition of insulin-stimulated glucose uptake in skeletal muscle, which is actually mediated by increasing blood flow through a NO-dependent pathway." (PMID 25202970, 2014). "Therapeutic interventions are needed to improve insulin sensitivity because insulin resistance eventually leads to T2DM." (PMID 24918297, 2014).
Insulin resistance (continued). "Several studies suggest that TNF-α and IL-6 improve lipolysis and the secretion of FFA, which promotes insulin resistance by interfering with glucose transport and insulin action." (PMID 25053966, 2014). "GDM and T2DM share a common genetic background, including glucose intolerance, insulin resistance, and impaired insulin secretion." (PMID 24695443, 2014). "XMetS restored the ability of insulin to lower glucose levels in these mice, indicating decreased insulin resistance." (PMID 24533136, 2014). "Insulin sensitivity was also evaluated by ipGTT and ipITT, and we demonstrated that HFD caused severe glucose intolerance and insulin resistance, which were reversed by rosiglitazone treatment." (PMID 25337938, 2014). "Collectively, these observations suggest that the rapa-treated mice were producing, storing, and releasing less insulin, likely explaining the increased hyperglycemia, while the untreated mice showed a pattern consistent with developing insulin resistance." (PMID 25473963, 2014). "The natural history of type 2 diabetes is characterized by increasing insulin resistance which is normally compensated for by increasing insulin secretion to maintain normal glucose tolerance." (PMID 24843074, 2014). "Activation of these inflammatory cytokines can directly induce insulin resistance and disturb intracellular insulin signaling pathways." (PMID 25053966, 2014). "Although the biological effects of PFOS on the elevated levels of fasting serum glucose and insulin levels were observed in both pups and adults of F1, the phenotypes of insulin resistance and glucose intolerance were only evident in the F1 adults." (PMID 24498028, 2014). "A metabolic syndrome is characterized partly by insulin resistance resulting from chronically elevated levels of plasma free fatty acids that, when released into liver and muscle tissue, inhibit insulin secretion." (PMID 25580230, 2014). "Insulin resistance is characterized by not only decreased glucose utilization by tissues in response to insulin but also myriad of events that increase significantly the risk for cardiovascular disease." (PMID 24959351, 2014). "Another approach has been to study a limited list of known adipocytokines during insulin sensitivity and insulin resistance." (PMID 24948903, 2014). "In the present study, HBCD-treated HFD-fed mice had increased random blood glucose and random blood insulin, and a tendency toward impaired insulin resistance." (PMID 24398136, 2014). "Experimental mice models have shown that recombinant resistin promotes insulin resistance and decreases insulin-stimulated glucose transporters in adipose tissue, while antiresistin antibodies produce the opposite effect." (PMID 24741627, 2014). "In patients with type 2 diabetes, insulin sensitivity is usually decreased due to insulin resistance." (PMID 25371752, 2014). "Other than that it helps in inhibiting progression of type 2 DM and the intake of trehalose has been shown to give better effects such as evoking lower insulin secretion, mitigating insulin resistance, and reducing osteoporosis development." (PMID 25243114, 2014). "Further, insulin sensitivity and insulin resistance was determined using the surrogate HOMA-IR method, as opposed to, for example, the hyperinsulinemic euglycemic clamp method." (PMID 24708607, 2014). "The increases of PGC-1 and SCD-1 are consistent with an insulin resistant phenotype in the liver and correlate with the more severe insulin resistance observed in CD1d−/− mice following HFD feeding." (PMID 24465369, 2014). "Insulin was able to increase cortical activity in lean animals while HFD-fed obese mice displayed insulin resistance." (PMID 24643026, 2014). "Short-term Intralipid infusion significantly increases FFA levels and insulin resistance by decreasing peripheral glucose uptake and down-regulating intracellular insulin signaling." (PMID 25144649, 2014).
Insulin resistance (continued). "Our results indicate that triterpenoid saponins from S. chinensis, especially compound 6, significantly ameliorate insulin resistance by restoring the activities of HK and PK to the levels observed in control insulin-sensitive cells." (PMID 24918297, 2014). "The increased demand for the production of insulin during insulin resistance and hyperglycemia can result to beta cell hypertrophy and proliferation, and finally to enlarged islets." (PMID 25144618, 2014). "Inflammation can not only impair insulin signaling and contribute to insulin resistance but can also trigger β cell apoptosis and reduce insulin secretion." (PMID 24759263, 2014). "Sixteen trials were included, in which 16 fasting blood glucose (n = 770), 10 fasting plasma insulin (n = 349), 9 glycated hemoglobin (n = 264), and 7 homeostasis model assessment of insulin resistance (n = 305) comparisons were reported." (PMID 25265315, 2014). "Disruption of the AMPD1 gene leads to a less severe state of insulin resistance, improved glucose tolerance and enhanced insulin clearance in mice fed a high fat diet." (PMID 25511531, 2014). "For instance, in both ob/ob and diet-induced obese mice, genetic deletion of TNF-α or its receptors significantly reduced insulin resistance and improved insulin signaling in muscle and adipose tissue." (PMID 24563869, 2014). "Impaired insulin secretion and insulin resistance are the two main metabolic disturbances in the pathogenesis of type 2 diabetes and often coexist." (PMID 25174260, 2014). "The increase in levels of both fasting blood glucose and endogenous insulin established the notion that chronic exposure to excess insulin induced insulin resistance in animals treated with glargine." (PMID 24741073, 2014). "The notion that animal protein stimulates insulin secretion and possibly insulin resistance was proposed decades ago." (PMID 25192735, 2014). "Fatty acids induce insulin resistance in skeletal muscle by the direct inhibition of insulin-activated glucose transport." (PMID 24809394, 2014). "Sp1 is relevant to adipocytokine transcription since it is a target of the insulin signaling cascade and many promoters of genes regulated during insulin resistance have Sp1 motifs." (PMID 25657638, 2014). "This ‘selective insulin resistance’ phenomenon mitigates insulin metabolic regulation, including its antagonistic effect in atherosclerosis." (PMID 24604418, 2014). "Although results of animal studies indicate that vaspin is an insulin-sensitizing adipocytokine, the real role of vaspin in human insulin resistance is still unclear." (PMID 24732788, 2014). "IL-6 is suggested to play a role in insulin resistance, as its circulating levels are positively related to adiposity and IL-6 is overexpressed in fat cells from insulin-resistant subjects." (PMID 24918199, 2014). "Taken together these data suggest that induction of MCD in skeletal muscle exacerbates HFD-induced insulin resistance evidenced by decreased insulin signaling." (PMID 25152047, 2014). "It is well known that AKT phosphorylation is reduced under conditions of insulin resistance and immediately restored upon onset of insulin sensitivity." (PMID 25143786, 2014). "Insulin sensitivity normally decreases during aging, and the prevalence of metabolic syndrome (MetS) and insulin resistance substantially increases." (PMID 24860814, 2014). "Insulin resistance not only becomes evident as reduced insulin–dependent glucose utilization, but also as higher fasting and/or less suppressible EGP, and higher lipid availability, such as circulating free fatty acids (FFA) and/or triglycerides." (PMID 25517727, 2014). "It has been shown that lipotoxicity can result in insulin resistance of skeletal muscle, hepatic steatosis and impairment of insulin secretion by β-cells." (PMID 26237395, 2014).
Insulin resistance (continued). "Ceramides are known to promote insulin resistance in a number of metabolically important tissues including skeletal muscle, the predominant site of insulin-stimulated glucose disposal." (PMID 25058613, 2014). "We conducted a single-arm open-label prospective pilot study to investigate the effects of testosterone supplementation on central and peripheral insulin sensitivity in older men with upper body obesity and insulin resistance." (PMID 25392748, 2014). "We and others have previously shown that insulin plays an essential role in the HFD-induced insulin resistance." (PMID 25055153, 2014). "These blood glucose and blood insulin values can be used to estimate peripheral insulin resistance using the HOMA-IR model." (PMID 24949727, 2014). "Recent data confirm that chronic elevation of intracellular ROS levels in adipocytes subsequent to mitochondrial dysfunction results in insulin resistance through attenuation of insulin signalling." (PMID 25548896, 2014). "The His447His polymorphism (also referred to as C161T, C1431T, or CAC478CAT, His449His) is a silent mutation at exon 6 and is considered a better predictor of fasting insulin levels and insulin resistance than Pro12Ala." (PMID 25197274, 2014). "For measures of fasting insulin, insulin resistance (HOMA index), and glucose tolerance, low testosterone tended to exacerbate and or testosterone treatment improved outcomes." (PMID 25224590, 2014). "Insulin resistance is a core component of the preclinical stages of type 2 diabetes (i.e., “prediabetes”) and is characterized by an impaired ability of insulin to stimulate glucose uptake into muscle and adipose tissue in all species." (PMID 24977043, 2014). "Levels of fasting glucose and insulin and measures of insulin resistance are used to test for early signs of diabetes and they have been subject to a recent MWAS." (PMID 25229548, 2014). "There is a clear association between insulin resistance and NAFLD, with impaired insulin signaling almost always occurring in conjunction with NAFLD." (PMID 25371775, 2014). "Treatment of HFD-fed hamsters with ruscogenin (3.0 mg/kg/day) had a beneficial effect on insulin resistance, as evidenced by a reduction in fasting plasma insulin levels, and improved levels of HOMA-IR." (PMID 25136608, 2014). "Since insulin resistance is a major metabolic abnormality of type 2 diabetes, there has been considerable interest in insulin sensitizing agents to counteract insulin resistance for the treatment of this disease." (PMID 25184241, 2014). "In the acromegalic patients, however, of all the insulin secretion parameters, only the Insulinogenic Index was different and higher by 60% in the patients with insulin resistance (p<0.01 vs. IS-ACRO)." (PMID 25517727, 2014). "Intracerebroventricular (icv) administration of bromocriptine to seasonal insulin resistant hamsters reduces body fat store levels, hyperinsulinemia, insulin resistance, and glucose intolerance." (PMID 25937836, 2014). "Many studies suggest that adiponectin is an important regulator of insulin sensitivity and glucose homeostasis, with several reports confirming an inverse relationship between insulin resistance and type II diabetes with plasma adiponectin levels." (PMID 24563869, 2014). "During periods of maladaptation, increased tissue glucocorticoids and circulating corticosterone will impair the insulin signaling pathway, leading to hypersecretion of insulin; a condition leading to insulin resistance." (PMID 24860550, 2014). "In patients, almost all insulin resistance reflects defects in insulin-stimulated glucose transport into skeletal muscle cells." (PMID 24809394, 2014). "There were significant differences in waist and hip circumference, BMI, plasma insulin and insulin resistance within the groups over time." (PMID 25560330, 2014).